PLPP4 (phospholipid phosphatase 4)
Diseases named in the same sentence as PLPP4 in open-access papers (continued):
Sharing a sentence is not in itself a finding about the gene and the disease.
glioma (continued). "To investigate the effects of overexpression or silencing of PLPP4 on proliferation, migration, and invasion of glioma LN229 cells, we first used CCK-8 cell proliferation assay to confirm that overexpression of PLPP4 enhanced cell proliferation and increased with time (P<0.05)." (PMID 34917513, 2021). "Besides, the relationship between PLPP4 and the pathological stage of the glioma and PAAD was assessed; we found the expression of PLPP4 decreased as the adenocarcinomas progressed in PAAD." (PMID 34917513, 2021). "PLPP4 is differentially elevated in glioma and PAAD tissues." (PMID 34917513, 2021). "Silencing PLPP4 inhibits the proliferation and tumorigenicity of glioma and PAAD cells in vitro." (PMID 34917513, 2021). "We identified the specificity of PLPP4 expression in glioma by single-cell sequencing analysis." (PMID 34917513, 2021). "The results showed that inhibiting PLPP4 expression could effectively reverse the proliferation, migration, and invasion of glioma LN229 cells." (PMID 34917513, 2021). "Furthermore, we investigated the prognostic values of PLPP4 in the glioma and PAAD cases." (PMID 34917513, 2021). "In addition, the expression levels of PLPP4 in glioma were also higher than normal tissues." (PMID 34917513, 2021). "Then we first examined PLPP4 expression levels in glioma cell lines by western blot, and LN229 of the glioma cell line was used for the further experiment." (PMID 34917513, 2021). "Our results further verify that overexpression of PLPP4 is observed in the glioma and PAAD tissues and cells and positively correlates with advanced clinicopathological features and poor prognosis in glioma and PAAD patients." (PMID 34917513, 2021). "In this study, we first investigated the expression of LPPs in the glioma and PAAD and found PLPP4 was over-expressed in the glioma and PAAD compared with the normal tissues." (PMID 34917513, 2021). "Multivariate Cox analysis showed that PLPP4 expression level (HR=1.041, 95%CI: 0.561~1.774, P=0.011), WHO grade, age, and lymph node invasion and metastasis influenced poor factors prognosis of glioma patients." (PMID 34917513, 2021). "Taken together, our findings indicate that PLPP4 plays an important role in the progression of glioma and PAAD and suggest that PLPP4 may serve as a potential target for human glioma and PAAD treatment." (PMID 34917513, 2021). "In conclusion, PLPP4 is highly expressed in PAAD and glioma." (PMID 34917513, 2021).
lung adenocarcinoma (2 papers, 2017 to 2021). A carcinoma that arises from the lung and is characterized by the presence of malignant glandular epithelial cells. "PLPP4 promotes proliferation and tumorigenesis via activating the influx of intracellular Ca2+ in lung adenocarcinoma (ADC) tissues." (PMID 34917513, 2021). "PLPP4 is differentially elevated in lung adenocarcinoma (ADC) and lung squamous cell carcinoma (SQC) tissues." (PMID 28851360, 2017).
Parkinson disease (2 papers, 2024 to 2025). A progressive degenerative disorder of the central nervous system characterized by loss of dopamine producing neurons in the substantia nigra and the presence of Lewy bodies in the substantia nigra and locus coeruleus. "Two Parkinson’s disease risk genes presented distinct patterns, with PLPP4 expressed in initial OPC cells and DNAH17 expressed in late oligodendrocytes." (PMID 39363111, 2024).
adenosquamous carcinoma (1 paper, 2017). A carcinoma composed of malignant glandular cells and malignant squamous cells. "We further examined PLPP4 expression in our 5 paired ADC tissues, 2 paired SQC tissues and 1 lung adenosquamous carcinoma tissue (Mix: P3) and found that the mRNA and protein expression levels of PLPP4 were differentially elevated in tumor tissues compared with those in the respective ANT." (PMID 28851360, 2017).
pancreatic cancer (1 paper, 2021). "First, immunohistochemistry showed that the expression of PLPP4 protein in PAAD tissues was significantly higher than that in normal pancreatic cancer tissues." (PMID 34917513, 2021). "In general, PLPP4 signature performed well at predicting the overall survival of pancreatic cancer." (PMID 34917513, 2021).
small cell lung carcinoma (1 paper, 2017). Small cell lung cancer (SCLC) is a highly aggressive malignant neoplasm, accounting for 10-15% of lung cancer cases, characterized byrapid growth, and early metastasis. "Immunohistochemical analysis of PLPP4 expression in 265 non-small cell lung cancer tissues was further examined." (PMID 28851360, 2017).
tumor (5 papers, 2017 to 2024). "Furthermore, we also predicted the molecular mechanism associated with PLPP4 in tumor progression." (PMID 34917513, 2021). "PLPP4 is widely expressed in a variety of tumor cells and plays a role in tumor genesis and invasion." (PMID 34917513, 2021). "The tumors formed by the PLPP4-silenced cells were smaller and had decreased tumor volumes and weights compared to those in the control group." (PMID 28851360, 2017). "PLPP4 is widely expressed in various tumor cells and plays a role in tumor genesis and invasion." (PMID 34917513, 2021). "Based on the expression level of PLPP4, we performed a subgroup analysis of PAAD based on tumor grade, age, race, gender, recurrence, and metastasis." (PMID 34917513, 2021). "PLPP3, PLPP4, and PLPP6 were differentially elevated in some cancers, particularly PLPP4 showed “with” and “without” expression in cancer or tumor tissues (T) compared to the respective adjacent normal tissues (N)." (PMID 34917513, 2021).
cancer (4 papers, 2017 to 2021). A tumor composed of atypical neoplastic, often pleomorphic cells that invade other tissues. "Therefore, our findings indicated that increased expression of PLPP4 was positively associated with advanced clinicopathological features in many cancers." (PMID 34917513, 2021). "The expression of phospholipid phosphatase 4 (PLPP4) protein is increased, and it promotes cancer cells metastasis probably by activating TRPC channels-mediated Ca2+ influx." (PMID 36046433, 2021). "PLPP4 has been involved in cancer-related inflammation and the infiltration of immune cells, thus affecting the clinical outcome of cancers." (PMID 34917513, 2021). "Next, we want to focus on the analysis of PLPP4 in different cancers because of the specificity of PLPP4 expression between cancer and the respective adjacent normal tissues." (PMID 34917513, 2021). "Phospholipid phosphatase 4 (PPAPDC1A or PLPP4) has been demonstrated to be involved in the malignant process of many cancers." (PMID 28851360, 2017). "Moreover, the correlation between PLPP4 and immune cell infiltration of cancers was also assessed." (PMID 34917513, 2021). "However, the clinical significance and biological role of PLPP4 in cancers remain blank." (PMID 28851360, 2017).
PLPP4 also shares sentences with these, for which no sentence is quoted: adenocarcinoma (1 paper); Alzheimer disease (1); cognitive decline (1); lung (1); lung squamous cell carcinoma (1); malignant glioma (1); ovarian carcinoma (1); pancreatic adenocarcinoma (1).